HOTAIR (HOX transcript antisense RNA)
Diseases named in the same sentence as HOTAIR in open-access papers (continued):
Sharing a sentence is not in itself a finding about the gene and the disease.
liver fibrosis (10 papers, 2018 to 2024). "In an investigation into liver fibrosis, one study explored the impact of HOTAIR, a long intergenic noncoding RNA, on HSCs." (PMID 38511056, 2024). "The study revealed a substantial increase in HOTAIR expression in both in vivo and in vitro HSCs during the progression of liver fibrosis." (PMID 38511056, 2024). "HOTAIR expression was significantly elevated in mouse models of liver fibrosis, human fibrotic livers, and TGF-β1-stimulated HSCs." (PMID 38511056, 2024). "HOTAIR, which is upregulated in various cancers and liver fibrosis, is a potential therapeutic target." (PMID 37958478, 2023). "Regarding the lncRNA HOTAIR, found upregulated in several cancers and in liver fibrosis, it has been proved as a potential therapeutic target." (PMID 36110328, 2022). "When TGF-β1 activated hepatic stellate cells (HSC) in the CCl4-induced mouse liver fibrosis model and in human fibrotic liver, HOTAIR expression decreased significantly." (PMID 30931332, 2019). "HOTAIR upregulation also correlates with the progression of liver fibrosis." (PMID 33540611, 2021). "Interestingly, increased HOTAIR expression was also observed in hepatocytes during liver fibrosis." (PMID 38511056, 2024). "Therefore, HOTAIR may be involved in the process of liver fibrosis, and of course it is necessary to further explore the role of HOTAIR in the progression of liver fibrosis in NAFLD." (PMID 30931332, 2019). "At present, several lncRNAs have been proved to be involved in the occurrence and development of liver fibrosis by controlling PI3K/Akt signaling pathway, such as lincrna-p21, HOTAIR, and H19." (PMID 34597331, 2021). "Like GAS5, lncRNA, including lncRNA-p21, PVT1, HOTAIR, and MALAT1, acts as a ceRNA regarding liver fibrosis." (PMID 32413995, 2020). "HOTAIR acts as a ceRNA to sponge miR-29b, which induces PTEN methylation via the attenuation of DNMT2b contributing to liver fibrosis." (PMID 32413995, 2020). "In liver tissues and cells, HOTAIR downregulates miR-29b expression and attenuates its control on epigenetic regulation, leading to enhanced PTEN methylation and contributing to the progression of liver fibrosis." (PMID 33540611, 2021). "Additionally, HOTAIR forms an RNA/DNA hybrid and recruits PRC2 to the MEG3 promoter, highlighting its role in the epigenetic modulation of gene expression in the context of liver fibrosis." (PMID 38511056, 2024).
Parkinson disease (10 papers, 2018 to 2025). A progressive degenerative disorder of the central nervous system characterized by loss of dopamine producing neurons in the substantia nigra and the presence of Lewy bodies in the substantia nigra and locus coeruleus. "LincRNA-p21, SNHG1 and HOTAIR have been linked to Parkinson’s disease (PD)." (PMID 39920595, 2025). "In addition, overexpression of HOTAIR has been reported to accelerate dyskinesia and facilitate dopaminergic neuron apoptosis in a Parkinson’s disease mouse model via activation of the ERK1/2 axis." (PMID 37880710, 2023). "In addition, HOTAIR also serves as ceRNA in multiple CNS disorders, such as Parkinson’s disease (PD), MS, and TBI." (PMID 35813070, 2022). "Therefore, it is predicted that LncRNA MALAT1 and lncRNA HOTAIR interact synergistically to downregulate the miR-205-5p and influence the neuroinflammation in parkinsonism." (PMID 34066949, 2021). "HOTAIR activates NLRP3‐mediated pyroptosis in SH‐SY5Y cells by negatively regulating miR‐326, thereby promoting neuronal injury in Parkinson's disease." (PMID 34296520, 2021). "Other examples of lncRNAs involved in controlling all autophagic stages are HOTAIR, MALAT1, NBR2, PTENP1, and recently NEAT1 activating autophagy in Parkinson’s disease via PINK1 protein." (PMID 32489713, 2020).
laryngeal squamous cell carcinoma (9 papers, 2013 to 2024). A squamous cell carcinoma that arises from the larynx. "HOTAIR is overexpressed and regulates PTEN methylation in laryngeal squamous cell carcinoma." (PMID 32462038, 2020).
lymphoma (9 papers, 2017 to 2023). A malignant (clonal) proliferation of B- lymphocytes or T- lymphocytes which involves the lymph nodes, bone marrow and/or extranodal sites. "Few molecular epidemiological studies linked HOTAIR rs920778 polymorphism with the risk of breast, cervical, and lung cancer; rs1899663 with lung, breast, and gastric cancer; and rs12816786 with lymphoma." (PMID 36980864, 2023). "The aim of present study was to investigate the association of single nucleotide polymorphisms in the HOTAIR gene with lymphoma." (PMID 34582651, 2021). "In the present study the association of HOTAIR polymorphisms and lymphoma risk in an Iranian population were evaluated." (PMID 34582651, 2021). "In the present study we aimed to determine the possible association between HOTAIR polymorphisms and lymphoma in a sample of Iranian population." (PMID 34582651, 2021). "Because to the best of our knowledge this is the first research concerning the HOTAIR polymorphisms and the risk of lymphoma susceptibility in the literature more studies with larger sample size in patients of different ethnic origins should be done to confirm our findings." (PMID 34582651, 2021). "Another study has shown that HOTAIR depletion can promote apoptosis of lymphoma cells via inactivation of the ERK signaling pathway." (PMID 37880710, 2023). "In addition it has been reported that over-expression of HOTAIR correlate with diagnosis and prognosis of acute leukemia and lymphoma." (PMID 34582651, 2021).
diabetic retinopathy (8 papers, 2021 to 2026). "High glucose-dependent upregulation of HOTAIR in human retinal endothelial cells, as well as increased HOTAIR levels in serum and vitreous samples from patients with diabetic retinopathy." (PMID 37627644, 2023). "Studies have confirmed that HOTAIR plays a role in diabetic retinopathy and leads to diabetic retinal endothelial cell dysfunction." (PMID 34296520, 2021). "In research about diabetic retinopathy, the expression of HOTAIR is raised in patients and used as a novel biomarker in diabetic retinopathy." (PMID 34496971, 2021). "Regulating HOTAIR may provide a therapeutic option to inhibit the development/progression of diabetic retinopathy." (PMID 41744800, 2026). "Furthermore, as an active recruiter of chromatin-modifying complexes, HOTAIR mediates angiogenesis in diabetic retinopathy." (PMID 35359879, 2022).
gastric tumor (8 papers, 2016 to 2024). "HOTAIR, as an oncogene, is involved in various gastric tumors, driving malignant characteristics of these cancers." (PMID 33204219, 2020). "Consistent with our results, we also found overexpression of lncRNAs such as H19, GAS5, TUG1, AP5M1 and MALAT1 and downregulation of LINCROR, POU3F3, HOTAIR, FALEC, NBAT1, and ZEB2-AS1 lncRNAs in TCGA gastric tumor datasets." (PMID 29719612, 2018). "Our method predicted CDKN2B-AS1, HOTAIR and MALAT1 as main correlated molecules with stomach neoplasms." (PMID 29671405, 2018).
oral squamous cell carcinoma (8 papers, 2015 to 2023). "In oral cancer, HOTAIR mediates the suppression of cell proliferation and promotion of apoptosis and promotes the invasion and metastasis of oral squamous cell carcinoma through metastasis-associated gene 2 (MTA2)." (PMID 36924407, 2023). "In oral squamous cell carcinoma (OSCC), overexpression of HOTAIR is tightly associated with the metastatic features of tumor cells, and is able to enhance cancer stemness." (PMID 31072041, 2019). "HOTAIR, for instance, promotes tumor cell invasion and metastasis by recruiting EZH2 and repressing E-cadherin in oral squamous cell carcinoma." (PMID 29490660, 2018).
cardiac hypertrophy (7 papers, 2016 to 2022). "Accordingly, we have observed the decrease of HOTAIR in a mouse model of cardiac hypertrophy due to pressure overload, indicating a possible involvement of HOTAIR in the left ventricle remodeling associated to HF." (PMID 27317124, 2016). "Overexpression of HOTAIR inhibits miR-19 with subsequent retrieval of the expression of PTEN (a direct target of miR-19), which is involved in HOTAIR-mediated inhibition of cardiac hypertrophy." (PMID 30013975, 2018). "HOTAIR expression decreased notably in sustained cardiac hypertrophy mouse models, in which miR-19 expression was increased and inversely correlated with HOTAIR expression." (PMID 30217221, 2018). "In addition, in cardiac hypertrophy that induces HF, HOTAIR is capable of repressing hypertrophy in cultured cardiomyocytes treated with angiotensin II (Ang II)." (PMID 35083842, 2022). "Moreover, both WNT and cardiac hypertrophy pathways were enriched categories in the gene ontologies analysis of mRNAs correlated to HOTAIR." (PMID 27317124, 2016).
oral cancer (7 papers, 2017 to 2024). "Silence of HOTAIR in oral carcinoma stem cells significantly inhibited their cancer stemness, invasiveness and tumorigenicity in xenograft mouse models." (PMID 35204785, 2022). "Silence of HOTAIR in oral carcinomas stem cells (OCSC) significantly inhibited their cancer stemness, invasiveness and tumourigenicity in xenotransplantation models." (PMID 29228709, 2017). "In regard to oral cancer, a multiple studies have suggested that HOTAIR was highly expressed in OSCC tissues and facilitated the growth of OSCC cells via reduction of cell apoptosis." (PMID 29228709, 2017). "Nevertheless, HOTAIR-mediated regulation of oral carcinomas stem cells (OCSC) still remains to be elucidated." (PMID 29228709, 2017). "Notably, EZH2 emerges as a significant gene involved in regulating the STAT3/HOTAIR axis, influencing HNSCC proliferation, differentiation, and promoting metastasis by modulating related oncogenes in oral cancer." (PMID 38600608, 2024).
pancreatic adenocarcinoma (7 papers, 2021 to 2024). "For example, HOTAIR was reported to promote cancer cell energy metabolism in pancreatic adenocarcinoma by upregulating hexokinase-2." (PMID 37529795, 2022). "HOTAIR alters cancer cell energy metabolism in pancreatic adenocarcinoma by the upregulation of HK2." (PMID 33652661, 2021). "Conversely, in GBM, mesothelioma (MESO), cervical squamous cell carcinoma and endocervical adenocarcinoma (CESC), LUAD and Pancreatic adenocarcinoma (PAAD), overexpression of HOTAIR was associated with longer OS, suggesting a potentially protective role of HOTAIR in these specific cancer contexts." (PMID 38696320, 2024). "Besides, in pancreatic adenocarcinoma, HOTAIR is highly expressed in tumor tissues and can promote energy metabolism of cancer cells by enhancing glucose uptake, lactate production, and ATP synthesis." (PMID 34496971, 2021). "Furthermore, HOTAIR expression increases with tumor progression, making it a valuable biomarker candidate that may be used for diagnosis and prognosis of pancreatic adenocarcinoma." (PMID 37189687, 2023). "Conversely, there was a significant negative correlation between HOXA11-AS and the stromal scores of ACC and pancreatic adenocarcinoma (PAAD), and HOTAIR and the stromal scores of ACC and sarcoma (SARC) (p < 0.001)." (PMID 34805277, 2021).
psoriasis (7 papers, 2020 to 2025). An autoimmune condition characterized by red, well-delineated plaques with silvery scales that are usually on the extensor surfaces and scalp. "Here, we conducted a comprehensive study to investigate and analyze the association between HOTAIR expression and psoriasis in Chinese psoriasis patients." (PMID 34395618, 2021). "At first, HOTAIR was reported as a cancer-related gene; however, further investigation revealed that HOTAIR is associated with other conditions as well, including pregnancy, psoriasis, and CAD." (PMID 34064346, 2021). "The goal of this study was to investigate the association between HOTAIR polymorphisms and psoriasis in a Chinese Han population by screening key candidate single-nucleotide polymorphism (SNPs) sites in HOTAIR." (PMID 34395618, 2021). "We first found that the SNP at the HOTAIR locus was associated with a risk of psoriasis in a selected Chinese Han population, which might provide a new potential target for the treatment of psoriasis." (PMID 34395618, 2021). "In this study, we genotyped three SNPs for HOTAIR in 269 psoriasis patients and 273 healthy controls, detected the correlation of rs12826786, rs4759314, and rs1899663 with the disease, and analyzed the risk of psoriasis according to different inheritance models." (PMID 34395618, 2021). "Although associations between HOTAIR and ANRIL genomic variants and risk of psoriasis have been pointed in the Iranian population, the molecular mechanism of such associations has not been identified." (PMID 32695942, 2020). "Several lncRNAs might act as psoriasis biomarkers and/or therapy targets, such as the IL−22-responsive SPRR2C, psoriasis susceptibility gene PRINS, NF-κB-dependent ANRIL, IL−17A-promoting H19, and the innate immune response-related HOTAIR and MALAT1." (PMID 37310201, 2023). "Similarly, the presence of SNPs modulated the expression or function of the HOX Transcript Antisense RNA (HOTAIR); three SNPs in HOTAIR were genotyped in 286 psoriasis patients and 300 control subjects, among which rs12836786 was a genomic variant significantly associated with the risk of psoriasis." (PMID 40725772, 2025). "An important lncRNA, HOTAIR is extensively involved in affecting tumour cell proliferation and apoptosis, and metastasis, but its involvement in psoriasis has not been well documented." (PMID 37310201, 2023).
squamous cell carcinoma (7 papers, 2013 to 2024). A carcinoma arising from squamous epithelial cells. "Findings from this systematic review and meta-analysis revealed that HOTAIR represents a potential biomarker of prognosis in patients with squamous cell carcinoma of the head and neck." (PMID 29069846, 2017). "Previous studies used a PTC-derived cell line (TPC1) and squamous carcinoma cell line (SW579) to elucidate the role of HOTAIR in aggressive TC; knockdown of HOTAIR significantly inhibited cell growth and invasion." (PMID 34069428, 2021). "We next performed qRT-PCR analysis to examine the expression of HOTAIR in four human NSCLC cell lines, including both adenocarcinoma and squamous carcinoma subtypes." (PMID 24103700, 2013). "Furthermore, there was no clear connection between up-regulation of HOTAIR and CC histology (adenocarcinoma [AD]/adenosquamous cell carcinom [ASC] vs squamous cell carcinoma [SCC]: OR = 0.92, 95%CI 0.58-1.46, P = 0.714) or FIGO stage (III/IV vs I/II: OR = 0.89, 95%CI 0.33-2.38, P = 0.813)." (PMID 29108287, 2017).
diabetic kidney disease (6 papers, 2021 to 2025). Progressive kidney disorder caused by vascular damage to the glomerular capillaries, in patients with diabetes mellitus. "In diabetic kidney disease, HOTAIR is elevated in human and murine glomeruli, yet podocyte-specific deletion yields a minimal phenotype, underscoring cell-type and context dependence." (PMID 41303683, 2025). "Related studies have also shown that HOTAIR is highly expressed in patients with diabetic nephropathy and in the kidney tissues of animals." (PMID 34296520, 2021). "Studies had pointed out that the expression of lncRNA HOTAIR was increased in human diabetic kidney disease and HG-induced podocytes, but the current research on the role of HOTAIR in DN has not been reported." (PMID 35193668, 2022). "On the contrary, Majumder and colleagues showed that dysregulated HOTAIR acts as a bystander in diabetic kidney disease without participating in the pathogenesis of this type of kidney abnormality." (PMID 35359879, 2022). "In addition, HOTAIR facilitated high glucose-mediated fibrosis and proliferation of mesangial cells via affecting miR-147a/WNT2B axis in diabetic nephropathy." (PMID 36313695, 2022).